IL6 (interleukin 6)
Diseases named in the same sentence as IL6 in open-access papers (continued):
Sharing a sentence is not in itself a finding about the gene and the disease.
tumor (continued). "Besides tumor cell-derived cytokines, growth factors, and chemokines, intra-tumoral metabolites such as lactate, as well as IL-6 and M-CSF, have been shown to impair DC function." (PMID 39768204, 2024). "In addition, IL-6 can also lead to immunosuppression such as by reducing the abundance of CD8+ tumour-infiltrating lymphocytes (TILs) in the TME while expanding the Tregs population, as demonstrated in other cancers." (PMID 38473281, 2024). "Moreover, in the colon carcinoma cell line CT26 model, 40% of mice exhibited complete tumor regression associated with increased levels of pro-inflammatory cytokines IFN-γ, IL-6, and TNF-α in tumor and serum, and enhanced CD8+ T-cell infiltration." (PMID 39267734, 2024). "Results demonstrated that mRNA-2752 could induce the expression of IL-23, IL-36γ, IL-22, IL-6, IFN-γ, TNF-α, and PD-L1, and cause tumor shrinkage." (PMID 39030582, 2024). "Similarly, studies show that IL6-induced chemoresistance is developed by cross-talk of MAPK/ERK and NFκB signaling; thus, upstream blockage of these pathways can potentiate the anti-tumor response of anti-IL6 and anti-IL6R antibodies." (PMID 39766086, 2024). "Similarly, in mice with IDO1 and IL-6 knockout, a decreased probability of tumor metastasis and improved survival rate were observed." (PMID 38883986, 2024). "At this time, much pre-clinical and clinical investigative work remains to determine whether IL-6 is a key driver of tumor progression and potential target for directed intervention in patients with AC." (PMID 38689325, 2024). "Furthermore, some natural products can inhibit immunosuppressive factor secretion: IL-10, TGF-β; promote anti-tumor factor secretion: IL-2, IL-5, IL-6, IL-12; reduce immunosuppressive immune cells: Treg, M2 microphage; increase anti-tumor CD8+ T-cells." (PMID 38426097, 2024). "IL-6 has been extensively identified as a potential tumor biomarker." (PMID 38928482, 2024). "A systematic analysis of IL-6 as a predictive biomarker in NSCLC patients also revealed that those with a low baseline concentration of IL-6 in serum specimens or tumor tissues could derive more benefit from immune checkpoint inhibitors (ICIs)." (PMID 39502692, 2024). "Cytokines like IL6 and TNFα are secreted in the tumour microenvironment." (PMID 38339282, 2024). "IL-6 plays a key role in the proliferation and metastasis of various tumor cells." (PMID 39440046, 2024). "On the other hand, MCs inhibit tumor invasion and growth through the secretion of IL-1 and IL-6." (PMID 39680287, 2024). "In addition, cancer‐associated fibroblasts (CAFs) produce HGF, VEGF, TGF‐β, IL6, CXCL1, CXCL12, and PD‐L2, promoting tumor growth and antagonizing antitumor immune responses by recruiting suppressive immune cells." (PMID 39170944, 2024). "To evaluate whether immune cells can sense the reduced IL‐6 expression in tumor cells, we treated THP‐1 and Jurkat cells with conditioned media from Mock or C1GALT1 knockout SAS cells." (PMID 37452653, 2024). "Its anticancer prowess was observed to disrupt the G1/S phase, inducing apoptotic pathways through caspase-3 activation, and orchestrating the downregulation of pivotal cellular regulators such as STAT3, P21, P27, IL-6, and AhR, thereby impeding tumor progression." (PMID 38653790, 2024). "A high number of copies of IL6 mRNA within the tumour-associated stroma, but not epithelium, was associated with reduced cancer-specific survival." (PMID 39766336, 2024). "Furthermore, the expression of inflammatory factors, namely NF-κB, TNF-α, and IL-6, in the tumor tissues was significantly attenuated." (PMID 38622523, 2024). "M2 macrophages are also the most important source of IL-6 secretion in the tumor microenvironment." (PMID 38627864, 2024).
tumor (continued). "M1 macrophages primarily demonstrate anti-tumor effects through the secretion of cytokines like tumor necrosis factor-α (TNF-α) and interleukin-6 (IL-6), whereas M2 macrophages primarily release anti-inflammatory cytokines such as interleukin-10 (IL-10), which have promoting effects on tumor growth." (PMID 38637848, 2024). "In addition, in a mouse model of caloric restriction, tumor-induced IL-6 was found to compromise its metabolism (ketogenic response), thus suppressing anti-tumor immunity." (PMID 38434964, 2024). "There is emerging evidence that tumour derived IL-1β drives the IL-6/STAT3 axis and thus may act as a master cytokine to increase other transcription factors." (PMID 39516433, 2024). "Additionally, tumor cells exposed to IL-1β and IL-6 acquire an invasive and chemoresistant phenotype." (PMID 39260693, 2024). "Mast cells may promote inflammation, inhibition of tumor cell growth, and tumor cell apoptosis by releasing cytokines, such as IL-1, IL-4, IL-6, IL-8, monocyte chemotactic protein-3 and -4 (MCP-3 and MCP-4), TGF-β, and chymase." (PMID 39440039, 2024). "The activation of nuclear factor-κB (NF-κB) and associated signaling pathways and cytokines, such as TNFα, IL-6, and IL-1β, plays a key role in the development of CAC, which leads to imbalances in cell proliferation and differentiation and tumor transformation initiation." (PMID 39063041, 2024). "In our investigation into the synergistic relationship between IL-6/IL-8 and tumor markers for predicting the effectiveness of immunochemotherapy in AGC, ROC curves were used to evaluate the effectiveness of CA50, CA199, CEA, IL-6, IL-8, and CA724, as well as the combinations of these agents." (PMID 38774604, 2024). "M1 macrophages secrete many cytokines, including interleukin 1-beta (IL-1β), tumor necrosis factor alpha and beta (TNF-α and TNF-β), and interleukin 6 (IL-6), and are regarded as anti-tumor or pro-inflammatory, while M2 are considered as pro-tumor or anti-inflammatory." (PMID 38842752, 2024). "BMSCs recruited to the tumor microenvironment differentiate into tumor-associated fibroblasts (TAF), which release IL-6, IL-10, C-C chemokine ligand 5 (CCL5), and extracellular matrix remodeling enzymes in the tumor microenvironment to affect tumor cell survival and angiogenesis." (PMID 38770000, 2024). "Since the role of IL-6 and IL-17 has been shown to activate multiple signaling pathways important for cancer development, the differentiation of anti-inflammatory subsets is responsible for stabilizing the phenotype of tumor suppressors." (PMID 38279220, 2024). "However, when cell pyroptosis occurs, cytokines such as IL-1β and interleukin 6 (IL-6) are released into the tumor microenvironment." (PMID 39526199, 2024). "Importantly, while C1Q+ macrophage differentiation was independent of IL-1R signaling in EGCs, we found that IL-1-activated tumor EGCs drive monocyte differentiation into pro-tumorigenic SPP1+ macrophages via IL-6." (PMID 39030280, 2024). "This IL-1R/IL-6 axis is found to be essential for the tumor-supportive functions of EGCs." (PMID 39030280, 2024). "M1-like TAMs secrete TNF-α, IL-6, and IL-12 to promote anti-tumor immune responses." (PMID 38890722, 2024). "On the other hand, intestinal epithelial Caco-2 cells exposed to IL-6 are reported to induce a substantial increase in secretory clusterin production, which promotes tumor cell survival, in addition to interfering with Bax-mediated cell death by suppressing the apoptosis-promoting function of Bax." (PMID 39451248, 2024). "It was also shown that low IL-6 expression is required for the strong anti-tumor effect of DSP-0509 in the combination with RT, but may be the result of the anti-tumor effect since IL-6 acts negatively on the activation of CTLs." (PMID 39054418, 2024).
tumor (continued). "In another study, exosomes containing HSP70 originated from heat-stressed colon cancer cells, abolished TGF-β1-induced Treg differentiation, and enhanced Th17 generation in the animal model by boosting IL-6 production in BMDCs, thereby improving anti-tumor response." (PMID 38741166, 2024). "IL-6 may inhibit anti-tumor immunity through effects on CD4+ T cell differentiation and CD8+ T cell cytotoxicity." (PMID 39088539, 2024). "Moreover, tumor cells partially rely on the IL-6/STAT3 axis to escape cell death induced by cytotoxic drugs." (PMID 38520006, 2024). "We demonstrate that IL-6 is strongly expressed in GC and promotes several tumor hallmarks." (PMID 38422751, 2024). "For example, it is notably suggested that consumption of UPFs was associated with an elevated level of inflammatory biomarkers, such as IL-6 concentration, which are involved in tumor progression at almost every step including initiation, progression, and metastasis." (PMID 37360305, 2023). "Moreover, in human MSCs-treated hepatocellular tissues, TNF-α, IL-6, and α5 integrin expression were elevated to promote tumor growth and metastasis in HCC." (PMID 38022534, 2023). "For example, Astragaloside IV, as an active extract of Astragali Radix, could inhibit the growth and proliferation of tumor cells and induce apoptosis of tumor cells, and promote immunity by regulating levels of IL-1β, IL-6, and TNF-α cytokines." (PMID 37907925, 2023). "In addition, tumour microenvironmental molecules such as IL-6 triggered RNCR3 expression during MDSCs specialization and further promote their immunosuppressive activity." (PMID 36817434, 2023). "We hypothesized that IL-6 produced by CAFs promotes tumor growth in the TME and is the target of anti-IL-6 receptor antibody therapy." (PMID 36764954, 2023). "Apart from this, IL-6 blockade is also deemed to have anti-tumour effects." (PMID 38414933, 2023). "However, significantly more tumor cell deaths and less secretions of cytokines (IL-6, IFN-γ, granzyme B and TNF-α) from the medium were observed in CRC cells with A20 overexpression than that in control cells and PBMCs co-culture system with matched HLA-A2." (PMID 37607946, 2023). "Indeed, the recruitment and activation of many inflammatory cytokines, such as IL-6, which regulate the tumor immune response and tumor development, is made possible by the presence of YAP in the nucleus." (PMID 38249077, 2023). "Interestingly, serum IL-6 correlated more strongly with the amount of αSMA in the tumor than with tumor weight." (PMID 36764954, 2023). "Furthermore, the CD10+GPR77+CAF subset has been found in human cancer tissue samples to contribute to tumor stem cell proliferation by secreting IL-6 and IL-8, hence contributing to tumor growth and resistance to chemotherapy." (PMID 37795038, 2023). "By STAT3 activation, Il-6 introduces expression of genes conducive to tumor progression." (PMID 37373969, 2023). "Thus, the effects of IL-6 are ambivalent depending on its release as tumor-induced interleukin or exercise-derived myokine." (PMID 37760634, 2023). "The tumor-activated HS-5 is enriched in soluble uPAR (SuPAR), IL-6, and hepatocyte growth factor (HGF), which might be responsible for chemoresistance induction." (PMID 37175439, 2023). "CAF heterogeneity can be categorized into the inflammatory CAF group with low αSMA expression and high IL-6 expression, the TGFβ-dependent myofibroblast CAFs with high αSMA expression, or tumor suppressive CAFs with inhibitory effects mediated through stroma-specific Hedgehog (Hh) activation." (PMID 37046676, 2023). "Systemic IL-6 and G-CSF levels are elevated during surgical wounding and chronic inflammation; thus, it would be interesting to contrast the inflammatory secretome produced following chemotherapy versus surgical wounding encountered during tumour resections." (PMID 37703292, 2023).
tumor (continued). "In addition, we have reported that miR-1246 increases IL-6 secretion of ECs in highly metastatic tumor EVs, resulting in induction of drug resistance through the activation of STAT3 and Akt." (PMID 37124539, 2023). "Moreover, Dreuw and co-authors demonstrated that fibroblasts, resulting from the differentiation of MSCs, mediated IL-6 secretion, leading to the overexpression of Bcl-2 and Bcl-xL in tumor cells and an inhibition of apoptosis following anti-cancer treatment." (PMID 37686315, 2023). "The specific evaluation of the IL-10 and IL-6 expression levels, both in macrophages and in tumor cells, revealed an opposite trend in the IL-10/IL-6 ratio in the co-culture of macrophages with the MG-63 cell line compared with co-culture with HOS and 143B cells following mifamurtide administration." (PMID 37835437, 2023). "Similarly, in non-small cell lung cancer, tumor-derived IL-6 recruits immune checkpoint molecule presenting MDSCs, which exert a systemic effect and promote brain metastases." (PMID 36260158, 2023). "IL-6 might induce tumor immunosuppression by decreasing effector T-cells by enhancing cancer glucose uptake and by increasing regulatory cells through HIF1α and VEGF function via hypoxia-pseudohypoxia-mediated HIF1α activation." (PMID 36764954, 2023). "Our data support the notion that the tumor microenvironment, in combination with serum, stimulates CSCs to secrete cytokines, such as IL-6 and CCL2, that act paracrine to cancer cells to enhance their malignant properties, including sphere formation, stem cell characteristics, and migration ability." (PMID 37639070, 2023). "As a component of the body’s inflammatory response triggered by the tumor, the production of proinflammatory cytokines (such as IL-6) may be a contributing factor to the lower serum albumin concentration." (PMID 37836576, 2023). "CAFs secrete a variety of cytokines, growth factors and chemokines that form fertile soil for the growth of tumor cells; for example, CAFs secrete interleukin-6 (IL-6) or interleukin-11 (IL-11), resulting in tumor progression and the development of chemotherapeutic resistance." (PMID 36717783, 2023). "Pro-inflammatory bacteria stimulate the production of cytokines and chemokines, such as IL-6, IL-8, IL-1b, and TNF-α, which recruit and activate various immune cells, including tumor-associated macrophages (TAMs), T cells, and myeloid-derived suppressor cells (MDSCs)." (PMID 37760801, 2023). "This resulted in activation of tumour‐promoting cytokines (IL‐6, IL‐8, MCP‐1 and CXCL1)." (PMID 37759347, 2023). "We observed that the IL-6 expression was substantially upregulated in TAMOE−CM compared to TAMEV−CM, indicating that the expression of IL-6 in TAMs may be regulated by tumor exosomal cSERPINE2." (PMID 36797769, 2023). "Furthermore, we described the mechanism by which IL-6 mediates tumor immunosuppression by focusing on metabolic competition between T-cells and tumor cells via hypoxia-pseudohypoxia-mediated HIF1α activation." (PMID 36764954, 2023). "IL-6 is highly expressed in DTC and associated with tumor invasiveness." (PMID 38250858, 2023). "Finally, a cleavage fragment of COL6A3 known as endotrophin recruits macrophages through induction of monocyte chemoattractant protein-1 (MCP1) and increases IL-6 and TNFα in the tumor microenvironment." (PMID 36901727, 2023). "However, IL-6 is a complex pleiotropic cytokine and has also been shown to provide anti-tumour immunity by mobilising T-cell responses with broad effects on T-cell survival, proliferation, differentiation, and recruitment." (PMID 37441083, 2023). "This leads to improved secretion of IL‐6 and IL‐8, which promotes tumor cell proliferation." (PMID 37088729, 2023). "However, more substantial differences in the expression levels of some genes (ICAM-1, MMP-2, MMP-9, IL-6, and CX-43) were observed, indicating the potential influence of the cancer cell type on secondary tumor progression." (PMID 38001146, 2023).
tumor (continued). "IL-6 could also induce stem cell properties and even further enhance aerobic glycolysis of tumor cells in turn." (PMID 36614179, 2023). "Previous research confirmed that anti–IL–6 antibodies had anti-tumor effects in MM." (PMID 38002012, 2023). "In addition, the activation and remodulation of these Ti-DCs by MIP leads to significant upregulation in the expression of IL-12 and IL-6 on these cells, both of which are key players for inducing acute inflammation to confer protective anti-tumor immunity." (PMID 37122749, 2023). "In addition, macrophages can contribute to tumor-promoting inflammation through the secretion of immunostimulatory cytokines, such as interleukin-6 (IL-6), and tumor necrosis factor-alpha (TNFα)." (PMID 37509382, 2023). "Overall, these studies showed that higher baseline IL-6 levels were associated with shorter survival while its increase during ICI treatment was associated with tumor progression, suggesting a role of IL-6 as a negative biomarker for immunotherapy." (PMID 37958363, 2023). "Since CD10+GPR77+ CAFs induce chemoresistance by secreting IL-6 and IL-8, we examined the production of these cytokines by RT-qPCR in NBFs treated with CM from different tumors and found that chemoresistant tumor CM significantly induced the production of IL-6 and IL-8." (PMID 36418470, 2023). "The IL6/JAK2/STAT3 signaling axis is best studied in the context of tumor metastasis and tumor pathology since it induces epithelial–mesenchymal transition (EMT), resulting in tumor metastasis by promoting the expression of EMT-inducing transcription factors, such as Snail, ZEB1, JunB, and Twist1." (PMID 38203502, 2023). "IL-6 promotes tumor development by activation of the PI3K/Akt, NF-kB, and Mek/ERK pathways." (PMID 37736898, 2023). "Furthermore, lower levels of PD1 + TIM3 + T/T/T, TIGIT + T/T, and IL-6 in the tumor microenvironment correlated with a potentially higher DCR, suggesting that patients have better clinical and survival benefits." (PMID 38110467, 2023). "The involvement of CKLF1 in tumor development may be related to its role in mediating the IL-6/JAK/STAT3 pathway." (PMID 36865551, 2023). "Because SC144/paclitaxel treatment reduced IL-6 levels in vivo, paclitaxel might act more effectively in reducing tumor size and volume." (PMID 36672405, 2023). "In addition, GSEA revealed that HER2neg TNBC tumor was mediating some processes involving in immune-related activities, such as IL-6-JAK-STAT3 signaling." (PMID 36998014, 2023). "A potential association between IL-6 and CCL2, secreted by tumor-associated fibroblasts, and high Ki-67 levels was found, speculating how tumor proliferation in PitNETs may be influenced by fibroblasts." (PMID 37958702, 2023). "It was shown that in ovarian cancer, miR-217 inhibits tumour-induced M2 macrophage polarisation by targeting IL-6 and regulating the JAK3/STAT3 signalling pathway and that in renal cell carcinoma, BMP-6 induces M2 polarisation through activation of the Smad5/STAT3 pathway by IL-10." (PMID 38143746, 2023). "In CRC, IL-6 levels are correlated with tumor stage, survival rate, and liver metastasis." (PMID 37460938, 2023). "Next, we asked whether the increased IL-6 levels were responsible for the tumor-promoting function of tumor exosomal cSERPINE2." (PMID 36797769, 2023). "IL-6 levels increased significantly after the tumor (p < 0.05)." (PMID 37033618, 2023). "Notably, administering tocilizumab or IL-6 inhibitor combined with anlotinib, as a new therapeutic option, can overcome anlotinib-resistant tumor progression." (PMID 37404767, 2023). "When a tumour undergoes surgical resection, the concentration of the immunomodulatory molecule IL-6 increases around the areas of trauma, and this increase in inflammation may lead to an increase in blood pressure and local bleeding." (PMID 38140009, 2023).